ZDHHC20 (zDHHC palmitoyltransferase 20)
Diseases named in the same sentence as ZDHHC20 in open-access papers (continued):
Sharing a sentence is not in itself a finding about the gene and the disease.
tumor (12 papers, 2020 to 2026). "Ablation of the Zdhhc20 gene caused a potent 10-fold reduction of tumour formation compared to sgControl mice." (PMID 34610265, 2021). "Among them, the expression of the palmitoyltransferase ZDHHC20 (protein name DHHC20) consistently increased in tumor spheroids supplemented with palmitate across all cell lines." (PMID 41826695, 2026). "Both ZDHHC9 and ZDHHC20 exhibit characteristics of potential tumor biomarkers, supported by multiple datasets and clinical correlations." (PMID 40335986, 2025). "Consistent with the in vitro findings, knockdown of ZDHHC20 resulted in a lower tumor weight and smaller pancreatic neoplastic lesion area and, notably, a longer survival time, in KPC mice." (PMID 38821916, 2024). "Ablating the Zdhhc20 gene effectively blocked tumour formation in the genetically engineered mouse model but demonstrating that blocking DHHC20 potently inhibits the growth of existing tumours is more relevant to its potential as a therapeutic strategy." (PMID 34610265, 2021). "In addition, we found that the knockdown of ZDHHC20 inhibited tumor growth in vivo by employing a cell-derived xenograft (CDX) model." (PMID 38821916, 2024). "Importantly, tumor formation in the same mouse model is similarly reduced by Zdhhc20 genetic ablation, further implicating ZDHHC20 in EGFR regulation." (PMID 39168183, 2024). "Of interest, reducing zDHHC20 levels impairs tumor formation in a KRAS-mutant mouse model." (PMID 33219126, 2021). "In line, overexpression of wildtype Tm4sf1 in Zdhhc20 silenced 4T1 tumor spheroids failed to rescue STAT3 phosphorylation, KAT2A gene and protein expression in the presence and absence of extra palmitate." (PMID 41826695, 2026). "This would suggest that reducing ZDHHC20 in vivo should have a negative effect on either tumour growth or progression, although it is not apparent from these studies if these effects stem from a loss of EGFR palmitoylation by DHHC20." (PMID 34610265, 2021). "Mice expressing EGFRC1025A failed to form tumours similar to what we observed in the Zdhhc20-ablated mice." (PMID 34610265, 2021). "ZDHHC17 and ZDHHC20 may act as oncoproteins 43, 44, but ZDHHC2 and ZDHHC13 can act as tumor suppressors 45-47." (PMID 32863941, 2020). "Therefore, we performed ChIP-qPCR in 4T1 and EMT6.5 tumor spheroids with and without extra palmitate upon Zdhhc20 silencing." (PMID 41826695, 2026). "However, the same ZDHHC gene may be amplified in some tumor types but deleted in others (e.g. ZDHHC17, ZDHHC20, and ZDHHC21)." (PMID 31938047, 2020).
cancer (7 papers, 2019 to 2026). A tumor composed of atypical neoplastic, often pleomorphic cells that invade other tissues. "zDHHC20 has been implicated in the development of cancers resistant to epidermal growth factor receptor (EGFR) inhibitor therapies." (PMID 36087837, 2022). "However, we observed that Zdhhc20 silencing in cancer cells decreased lung metastasis induced by intravenous cancer cell injection as well as spontaneous metastasis from mammary fat pad injections." (PMID 41826695, 2026). "Moreover, the knockdown of Zdhhc20 in cancer cells decreased lung metastasis growth based on number, average lung metastases size and normalized area of total lung metastasis (metastasis area over total lung area) in control diet and in particular in HFD fed mice by 5 and 17-fold, respectively." (PMID 41826695, 2026). "Specifically, we injected Zdhhc20 silenced, Tm4sf1 palmitoylation mutant (C79A+C88A) expressing and control EMT6.5 and/or 4T1 cancer cells into the mammary fat pad and/or intravenously to mice." (PMID 41826695, 2026). "In line, we further observed that silencing Zdhhc20 decreased the plasma membrane localization of TM4SF1 in 4T1 and EMT6.5 cancer cells based on immunofluorescence." (PMID 41826695, 2026). "Subsequently, we injected control and Zdhhc20 silenced 4T1 and EMT6.5 cancer cells intravenously or into the mammary fat pad of HFD or control diet fed mice." (PMID 41826695, 2026). "ZDHHC20 inhibits chaperone-mediated autophagy of YTHDF3 through S-palmitoylation of Cys474, which can result in abnormal accumulation of the oncogenic product MYC and thereby support the malignant phenotypes of cancer cells." (PMID 38821916, 2024). "ZDHHC20 inhibits the chaperone-mediated autophagic degradation of YTHDF3 through S-palmitoylation of Cys474, which can result in abnormal accumulation of the oncogenic product MYC and thereby promote the malignant phenotypes of cancer cells." (PMID 38821916, 2024). "Moreover, we examined the function of ZDHHC7, ZDHHC20 and ZDHHC21 in human organ development and cancer using PubMed in NCBI." (PMID 36286021, 2022).
infection (1 paper, 2023). The state of being infected such as from the introduction of a foreign agent such as serum, vaccine, antigenic substance or organism. "We conclude that the ZDHHC20 enzyme isoform that is expressed at late stages of infection by SARS-CoV-2 ensures that Spike is extensively S-acylated to optimize its fusogenic capacity." (PMID 37952051, 2023). "Such higher molecular weight species of ZDHHC20 became visible at 8 h post infection of Vero E6 cells and could also be seen upon infection of more physiologically relevant cells such as human lung-derived Calu-3 or primary airway human epithelial cells." (PMID 37952051, 2023).
psychiatric disease (1 paper, 2025). "ZDHHC20 emerges as a potential therapeutic target, highlighting the value of multi‐omics in psychiatric disease research and suggesting avenues for targeted interventions addressing both neuronal and immune contributions." (PMID 40842128, 2025).
ZDHHC20 also shares sentences with these, for which no sentence is quoted: Hypertension (1 paper); intestinal infections (1); viral infection (1).